ADIPOR2 (adiponectin receptor 2)
Diseases named in the same sentence as ADIPOR2 in open-access papers (continued):
Sharing a sentence is not in itself a finding about the gene and the disease.
thyroid cancer (3 papers, 2021 to 2024). "In this study, we identified adiponectin receptor 1 (AdipoR1) and AdipoR2 on the surface of thyroid cancer cell lines." (PMID 39349421, 2024). "AdipoR1 and AdipoR2 were expressed in normal thyroid cells, Nthy-oris-3 (N9), and thyroid cancer cells, TPC-1, K-1, KTC-1 and BCPAP." (PMID 39349421, 2024). "This study shows that AdipoRon can induce autophagy in thyroid cancer cells via AdipoR2 and upregulating ULK1, thereby inhibiting tumor growth." (PMID 39349421, 2024). "In cell function experiments, AdipoRon, a small molecule agonist of AdipoR1 and AdipoR2, inhibited proliferation, clone formation, migration, and invasion in thyroid cancer cells, and induced differentiation in thyroid cancer cells." (PMID 39349421, 2024). "q-RT-PCR showed that the vast majority of the thyroid cancer cell lines tested, although with heterogeneity, expressed leptin and Acrp30 (AdipoR1, AdipoR2, and T-Cadherin) receptors when compared to Nthy-ori 3-1." (PMID 33587254, 2021). "We identified AdipoR1 and AdipoR2 on the surface of thyroid cancer cells." (PMID 39349421, 2024). "This suggests that AdipoRon activates ULK1 via AdipoR2 to induce autophagy in thyroid cancer cells." (PMID 39349421, 2024). "Immunofluorescence staining showed AdipoR1 and AdipoR2 on the surface of thyroid cancer cells." (PMID 39349421, 2024). "AdipoR2 knockdown reduced AdipoRon-induced autophagy in thyroid cancer cells." (PMID 39349421, 2024). "AdipoRon induced autophagy in thyroid cancer cells via AdipoR2 and by upregulating ULK1." (PMID 39349421, 2024). "Adiponectin receptor 2 (AdipoR2) was significantly downregulated in thyroid cancer tissues." (PMID 39349421, 2024). "Further immunohistochemical staining results showed that AdipoR1 and AdipoR2 expression is barely detectable in tumor-adjacent normal thyroid tissue; however, AdipoR1 expression is found in 27% of thyroid cancer tissues, and AdipoR2 expression is found in 47% of such tissues." (PMID 33815885, 2021).
adenoma (2 papers, 2011 to 2014). A neoplasm arising from the epithelium. "AdipoR1 and AdipoR2 expression by immunohistochemical staining were localized in the colon epithelium and was positive in all (100%) of the control and advanced adenoma tissues and in 62.8% and 88.5% of CRC tissues." (PMID 25370174, 2014). "AdipoR1 and AdipoR2 mRNA expression levels were significantly lower in the advanced adenoma and CRC groups than those in the controls." (PMID 25370174, 2014). "We examined AdipoR1 and AdipoR2 mRNA and protein expression levels in specimens from control, advanced adenoma, and CRC tissues by qRT-PCR and immunohistochemical staining." (PMID 25370174, 2014).
Alzheimer disease (2 papers, 2020 to 2023). A progressive, neurodegenerative disease characterized by loss of function and death of nerve cells in several areas of the brain leading to loss of cognitive function such as memory and language. "In the aged 5XFAD mouse model of Alzheimer’s disease, AdipoR2 was observed highly expressed in activated astrocytes." (PMID 36896172, 2023). "We report an altered metabolic environment in the brains of the 5XFAD mouse model of Alzheimer’s disease, where we observe significantly decreased neuronal expression of the adiponectin receptors AdipoR1 and AdipoR2, and overexpression of AdipoR2 in activated astrocytes." (PMID 32664663, 2020).
Anxiety (2 papers, 2019 to 2022). Intense feelings of nervousness, tension, or panic often arise in response to interpersonal stresses. "Another explanation is that anxiety behavior may be differentially regulated by AdipoR1 and AdipoR2." (PMID 29988086, 2019).
asthma (2 papers, 2023 to 2024). "AdipoR1 is expressed in airway epithelial cells in chronic obstructive pulmonary disease; while AdipoR2 is more highly expressed in people with asthma." (PMID 37149591, 2023). "The correlation between IgE and APN is scarce and only seen in a small number of studies of allergic diseases such as asthma, and the interaction between AdipoR2 and IgE in infectious diseases may be a future direction of research." (PMID 39840070, 2024).
autoimmune disease (2 papers, 2019 to 2021). A disorder resulting from loss of function or tissue destruction of an organ or multiple organs, arising from humoral or cellular immune responses of the individual to their own tissue constituents. "AdipoR1 and AdipoR2 expression was found to be decreased on the surface of B lymphocytes of patients with autoimmune disorders, namely, rheumatoid arthritis and type 1 diabetes." (PMID 31827477, 2019).
colorectal cancer (2 papers, 2016 to 2023). A primary or metastatic malignant neoplasm that affects the colon or rectum. "Recently, ADIPOR1 and ADIPOR2 were discovered to be strongly linked to metabolic and immunological homeostasis in colorectal cancer." (PMID 36896172, 2023). "However, their relationship to the detoxification enzyme Glyoxalase (GLO)-I and Adiponectin receptors (AdipoR1, AdipoR2) in colorectal carcinoma (CRC) is currently understudied." (PMID 26931562, 2016).
endothelial dysfunction (2 papers, 2016 to 2022). In vascular diseases, endothelial dysfunction is a systemic pathological state of the endothelium (the inner lining of blood vessels) and can be broadly defined as an imbalance between vasodilating and vasoconstricting substances produced by (or acting on) the endothelium. "The results of this study indicated that resveratrol increased circulating adiponectin levels and protected against DN by ameliorating inflammation, oxidative stress, apoptosis and endothelial dysfunction via activating AMPK–SIRT1–PPARα through AdipoR1 and AdipoR2." (PMID 27286657, 2016).
epithelial ovarian cancer (2 papers, 2018 to 2021). "This study is the first to report a lower expression of AdipoR1 and AdipoR2 in epithelial ovarian cancer cells compared with granulosa tumor cells." (PMID 29603059, 2018). "The expression of adiponectin receptors AdipoR1 and AdipoR2 has been reported in the human ovary and ovarian cancer tissues." (PMID 29603059, 2018). "There is some research that proves a significant decrease in expression of AdipoR1 and AdipoR2 observed in ovarian cancer cell lines and, more precisely, expression of those receptors was lower in the epithelial ovarian cancer cell line compared with granulosa tumor cell line." (PMID 33809784, 2021). "Additionally, our results indicated that both AdipoR1 and AdipoR2 are expressed in various epithelial ovarian cancer cell lines, and that their expression in these cell lines was lower than in the granulosa tumor cell line (COV434)." (PMID 29603059, 2018). "We aimed to investigate whether adiponectin and its receptors, AdipoR1 and AdipoR2, are expressed in human epithelial ovarian cancer cell lines." (PMID 29603059, 2018). "Second, we investigated whether BPA and its analogs could regulate the expression of AdipoR1 and AdipoR2 in epithelial ovarian cancer cells." (PMID 29603059, 2018). "Additionally, we found that AdipoR1 and AdipoR2 expression is lower in epithelial ovarian cancer cells than in granulosa tumor cells." (PMID 29603059, 2018). "Finally, we investigated whether E2, P4, and IGF-1 can regulate AdipoR1 and AdipoR2 expression and modulate the effects of adiponectin on the proliferation of ovarian cancer cells." (PMID 29603059, 2018).
glioblastoma (2 papers, 2021 to 2023). The most malignant astrocytic tumor (WHO grade IV). "Thus, there is a possibility that AdipoR2 inhibits human glioblastoma cell growth through the AMPK/mTOR pathway." (PMID 33752745, 2021).
glioma (2 papers, 2021 to 2022). A benign or malignant brain and spinal cord tumor that arises from glial cells (astrocytes, oligodendrocytes, ependymal cells). "AdipoR2, one of two Acrp30 receptors, is less expressed in high-grade glioma than low-grade glioma or normal brain tissue; higher expression of AdipoR2 is associated with a favorable prognosis." (PMID 36105407, 2022). "Further biological experiments have shown that AdipoR2 overexpression inhibits glioma cell proliferation through the adenosine monophosphate associated protein kinase (AMPK)–mammalian Target of Rapamycin (mTOR) signaling pathway." (PMID 36105407, 2022). "First, we analysed AdipoR2 expression levels in whole genome gene profiling of 158 glioma tissue samples." (PMID 33752745, 2021). "Most importantly, we investigated the effect of AdipoR2 overexpression on glioma cell proliferation." (PMID 33752745, 2021). "We also investigated the prognostic value of AdipoR2 in the 158 glioma samples by Kaplan–Meier survival analysis." (PMID 33752745, 2021). "We found 648 upregulated genes and 436 downregulated genes correlated with AdipoR2 expression in 158 glioma samples." (PMID 33752745, 2021). "In this study, we found that the expression of AdipoR2 correlates with glioma grade, so we further investigated the biological effect of AdipoR2 overexpression in U251 human cell lines." (PMID 33752745, 2021). "To identify the mechanism of AdipoR2 involvement in glioma, we first screened differentially expressed genes and found 648 upregulated genes and 436 downregulated genes related to AdipoR2 expression in the 158 glioma samples." (PMID 33752745, 2021). "In addition, we also investigated the mechanisms behind the antiproliferative effects of AdipoR2 in U251 cells (a human glioma cell line) using colony formation and WST-8 growth assays." (PMID 33752745, 2021). "We investigate the effect of AdipoR2 overexpression on the glioma cell proliferation." (PMID 33752745, 2021). "In this study, we found that AdipoR2 expression correlates with glioma grade." (PMID 33752745, 2021). "In addition, we also used a colony formation assay to determine the role of AdipoR2 in glioma cell proliferation." (PMID 33752745, 2021). "In our study, we found that AdipoR2 inhibited glioma cell proliferation." (PMID 33752745, 2021).
ischemic stroke (2 papers, 2019 to 2022). A stroke disorder caused by obstruction of blood flow to the brain, due to thrombotic (local blood clot formation) or embolic (due to a blood clot or other material traveling from another site) event. "Previously the relation between ischemic stroke and ADIPOR2 expression has been established, which might result in impaired glycolysis enzymes’ expression, glucose uptake and lactate production, and neuronal apoptosis." (PMID 35562921, 2022). "A correlation between ADIPOR2 expression and ischemic stroke has also been previously established." (PMID 31168302, 2019).
laryngeal carcinoma (2 papers, 2019 to 2021). Carcinoma that arises from the laryngeal epithelium. "In laryngeal carcinoma, miR-423-3p increases cell proliferation, invasion, and migration via modulation of AdipoR2." (PMID 35008806, 2021).
lipid metabolism disorder (2 papers, 2021 to 2022). "Further analysis revealed that the vast majority of genes regulating glucose metabolism were elevated in the dystrophic mice (except for Adipor2), whereas factors related to lipid metabolism disorder displayed both upregulated and downregulated patterns." (PMID 35273230, 2022).
liver diseases (2 papers, 2013 to 2019). "AdipoR1 is abundantly expressed in heart and skeletal muscle, whereas AdipoR2 is supposed to be the main receptor in the liver, suggesting an association with the pathology of liver diseases." (PMID 30894877, 2019).
non-small cell lung carcinoma (2 papers, 2013 to 2016). A group of at least three distinct histological types of lung cancer, including non-small cell squamous cell carcinoma, adenocarcinoma, and large cell carcinoma. "A study of non-small cell lung cancer also indicates that patients with higher expression of AdipoR1 have longer overall survival and AdipoR2 expression is inversely correlated with tumor size." (PMID 27119501, 2016).
polycystic ovaries (2 papers, 2013 to 2023). "A significantly lower proportion of theca cells expressed adiponectin receptors 1 and 2 (AdipoR1, AdipoR2) in polycystic ovaries than in normal ovaries." (PMID 24260388, 2013). "In the case of AdipoR2, the proportion of immuno-positive theca cells was 0.65 (0.52, 0.78) in polycystic ovaries and 0.77 (0.69, 0.85) in the normal controls (p = 0.049; Mann-Whitney test)." (PMID 24260388, 2013).
rheumatoid arthritis (2 papers, 2019 to 2022). A chronic, systemic autoimmune disorder characterized by inflammation in the synovial membranes and articular surfaces. "Additionally, we examined the expression of adiponectin receptors AdipoR1 and AdipoR2 at the level of mRNA and in the immunohistochemical analysis in synovium samples and infrapatellar fat pad samples from patients with osteoarthritis (OA) and rheumatoid arthritis (RA)." (PMID 35628866, 2022).
type 1 diabetes (2 papers, 2019 to 2025). "In both type 2 and type 1 diabetes models, knockdown of AdipoR1 nearly abrogated the pro-repair effect of ADPN on corneal epithelial injury, whereas AdipoR2 silencing had no such impact, indicating that ADPN promotes corneal epithelial repair specifically through AdipoR1." (PMID 41146365, 2025).
advanced heart failure (1 paper, 2013). Patients with advanced heart failure have severe limitations, experiences symptoms even while at rest and are mostly bedbound patients. "However, patients with advanced heart failure present increased adiponectin with reduced expression of AdipoR1 and AdipoR2 as well as reduced activation of AMP kinase, a known downstream signaling molecule, suggesting a functional adiponectin resistance in advanced heart failure." (PMID 23843680, 2013).
anxiety disorder (1 paper, 2025). A category of psychiatric disorders which are characterized by anxious feelings or fear often accompanied by physical symptoms associated with anxiety. "The TMCC1, OCA2 and ADIPOR2 genes have also been identified in a recent cross-anxiety disorder EWAS." (PMID 40281224, 2025).
Cerebral ischemia (1 paper, 2023). Restriction of arterial blood supply to the brain associated with insufficient oxygenation to support the metabolic requirements of the tissue. "AdipoR2 can lead to the activation of peroxisome proliferator-activated receptor γ (PPARγ), which has been demonstrated in rats with cerebral ischemia to effectively inhibit neuroinflammation by suppressing the release of inflammatory factors." (PMID 38203348, 2023). "Therefore, circ_0000831 can reduce neuroinflammation in cerebral ischemia through the miR-16–5p/ AdipoR2/PPARγ axis." (PMID 38203348, 2023).
chondrosarcoma (1 paper, 2015). A malignant cartilaginous matrix-producing mesenchymal neoplasm arising from the bone and soft tissue. "In addition, CM from chondrosarcoma cells demonstrated that AdipoR1 and AdipoR2 siRNA significantly reduced adiponectin-mediated migration and tube formation of EPCs." (PMID 26468982, 2015).
clear cell adenocarcinoma (1 paper, 2017). A malignant neoplasm composed of glandular epithelial clear cells. "We found differences of AdipoR2 expression in 786-O and ACHN that might be associated to differences in the origin of both cell lines: while 786-O is derived from a primary clear cell adenocarcinoma (primary tumor); ACHN is a line derived from pleural effusion, i.e. a metastatic site." (PMID 29212223, 2017).
disc degeneration (1 paper, 2016). "Expression levels of AdipoR1 and AdipoR2 in both the NP and AF were gradually decreased with increased disc degeneration." (PMID 27876065, 2016). "In the NP and AF, AdipoR1 and AdipoR2 expression gradually decreased with increased severity of disc degeneration." (PMID 27876065, 2016). "Using a rat tail temporary static compression model, AdipoR1 and AdipoR2 expression were found to decrease according to disc degeneration severity." (PMID 27876065, 2016).
endometriosis (1 paper, 2016). The growth of functional endometrial tissue in anatomic sites outside the uterine body. "Adiponectin can suppress endometriosis by inhibiting ESC proliferation and increased AdipoR1 and AdipoR2 expression." (PMID 26459399, 2016).
epididymitis (1 paper, 2023). Inflammation of the epididymis. "Rahmanifar and Tabandeh reported that ADIPOQ, ADIPOR1 and ADIPOR2 transcripts are present in the testes, epididymitis, and vesicular and bulbourethral glands." (PMID 36830390, 2023).
epilepsy (1 paper, 2022). A brain disorder characterized by episodes of abnormally increased neuronal discharge resulting in transient episodes of sensory or motor neurological dysfunction, or psychic dysfunction. "We found that ADIPOR1 and ADIPOR2, as cognate receptors of adiponectin, were highly expressed in the epilepsy group." (PMID 36138892, 2022).
fibrosis (1 paper, 2025). the formation of excess fibrous connective tissue in an organ or tissue in a reparative or reactive process. "APN interferes with the expression of TIMP1 and TGFB1 in IBD by targeting AdipoR2, so emodin succinate monoethyl ester (ESME), an AdipoR2 agonist possibly recedes the severity of colonic fibrosis in UC and fistulae in CD by restoring balance of TIMP1 and TGFB1." (PMID 40713669, 2025).
gastric ulcer (1 paper, 2021). An ulcerated lesion in the mucosal surface of the stomach. "Our data suggest that AdipoR1 and AdipoR2 activation may be an attractive therapeutic strategy to inhibit development of gastric ulcers." (PMID 34063466, 2021).
Hypercholesterolemia (1 paper, 2013). An increased concentration of cholesterol in the blood. "Thus, the severe hypercholesterolemia in ApoE-/- mice attenuated the hypocholesterolemic phenotype seen in AdipoR2-/- mice." (PMID 24324556, 2013).
Hypertension (1 paper, 2022). The presence of chronic increased pressure in the systemic arterial system. "Our results are consistent with those of a previous study that reported reduced expression of ADIPOQ and its receptors (AdipoR1 and AdipoR2) within the perivascular adipocytes of mice with angiotensin II-induced hypertension." (PMID 36157437, 2022).
leukemia (1 paper, 2025). A malignant (clonal) hematologic disorder, involving hematopoietic stem cells and characterized by the presence of primitive or atypical myeloid or lymphoid cells in the bone marrow and the blood. "Finally, we aimed to determine whether AdipoRon’s effects on angiogenesis in leukemia are mediated by AdipoR1 and/or AdipoR2." (PMID 41217652, 2025). "The lack of a significant effect following AdipoR2 silencing further confirms that AdipoRon primarily acts via AdipoR1 to regulate angiogenesis in leukemia cells." (PMID 41217652, 2025). "Finally, silencing of AdipoR1, but not AdipoR2, diminishes the AdipoRon-induced upregulation of the angiogenesis-related factors, suggesting that AdipoR1 is the primary receptor mediating the effects of adiponectin in leukemia cells." (PMID 41217652, 2025).
lung carcinoma (1 paper, 2019). "Therefore, We speculate miR-423-3p may also function as an oncogene role in lung cancer progression through regulating expression of AdipoR2." (PMID 31164163, 2019).
morbid obesity (1 paper, 2023). An excess of body weight, normally defined as an individual with a body mass index greater than 35 or a body weight greater than one hundred percent of ideal body weight. "At the same time, we observed a positive AdipoR2 immunoexpression for adipocytes from control group and a very low AdipoR2 immunoexpression for the group with morbid obesity." (PMID 37109222, 2023). "An important finding was the negative adipoR1 and adipoR2 immunoexpression in PVAT adipocytes of patients with morbid obesity." (PMID 37109222, 2023).
myocardial infarction (1 paper, 2020). Gross necrosis of the myocardium, as a result of interruption of the blood supply to the area, as in coronary thrombosis. "SOD1 overexpression, RELA blockade, and diminished MyD88-mediated inflammation can enhance functional and metabolic recovery and greatly decreased myocardial infarction, while ADIPOR2 is required for revascularization." (PMID 32565767, 2020).